MKNK1 (MAPK interacting serine/threonine kinase 1)
Description:
May play a role in the response to environmental stress and cytokines. Appears to regulate translation by phosphorylating EIF4E, thus increasing the affinity of this protein for the 7-methylguanosine-containing mRNA cap.
Synonyms: Mnk1
Tractability: Small molecule: a drug acting on it is in phase 2 or 3 trials; a structure with a bound ligand is known; a high-quality ligand is known; it belongs to a druggable protein family. PROTAC: ubiquitination databases record sites on it; its protein half-life has been measured; a small molecule that binds it is known.
Target class: Protein Kinase; CAMK protein kinase group; CAMK protein kinase MNK subfamily; Enzyme; Kinase; CAMK protein kinase MAPKAPK family
Chemical probes: tomivosertib (high quality)
Gene: Protein-coding gene on chromosome 1 (46,557,407 to 46,616,843, reverse strand). Ensembl gene ENSG00000079277.
Subcellular location: Cytoplasm (Isoform 2); Cytoplasm (Isoform 3); Nucleus
Subcellular location (Human Protein Atlas): Nucleoplasm
Pathways (Reactome):
Signal Transduction: Spry regulation of FGF signaling
Gene Ontology:
Molecular function: ATP binding; protein binding; protein serine kinase activity; protein serine/threonine kinase activity; protein kinase activity
Biological process: intracellular signal transduction; protein phosphorylation
Cellular component: nucleoplasm; cytosol; cytoplasm; nucleus
Genetic constraint (gnomAD): Loss-of-function variants: 29 observed, 44.7 expected, observed/expected ratio (o/e) 0.65, 90% interval 0.48 to 0.88. The upper end of that interval is the gene's LOEUF score, 0.88, which puts it in group 3 of 6, group 1 being the genes least tolerant of losing a copy. Missense variants: 388 observed, 490.79 expected, observed/expected ratio (o/e) 0.79, 90% interval 0.73 to 0.86. Synonymous variants: 160 observed, 189.58 expected, observed/expected ratio (o/e) 0.84, 90% interval 0.74 to 0.96.
Homologues: Orthologues: chimpanzee MKNK1 (99% identical), macaque MKNK1 (99% identical), dog MKNK1 (93% identical), mouse Mknk1 (93% identical), pig MKNK1 (93% identical), zebrafish si:ch73-60h1.1 (28% identical), Caenorhabditis elegans mak-2 (25% identical). Paralogues in human: MKNK2 (71% identical), CAMK4 (28% identical), MAPKAPK2 (28% identical), MAPKAPK5 (27% identical), MAPKAPK3 (27% identical), DCX (16% identical).
Diseases named in the same sentence as MKNK1 in open-access papers:
MKNK1 is named in the same sentence as 71 diseases in open-access papers, as found by Europe PMC text mining. Sharing a sentence is not in itself a finding about the gene and the disease. The quoted sentences say what the papers report.
breast carcinoma (18 papers, 2014 to 2025). "Pharmacologically induced degradation of MKNK1 is known to impair cell migration and promote cell death in breast cancer cells." (PMID 31827134, 2019). "Additionally, Mknk1 is involved in regulating inflammatory responses and is differentially expressed in the periphery (e.g., blood, dorsal root ganglia) in breast cancer survivors and mice with paclitaxel-induced peripheral neuropathy compared with controls." (PMID 40908146, 2025).
glioma (8 papers, 2018 to 2023). A benign or malignant brain and spinal cord tumor that arises from glial cells (astrocytes, oligodendrocytes, ependymal cells). "Across GBM subtypes, both MKNK1 and MKNK2 genes are highly expressed in mesenchymal subtype GBM, while only the MKNK1 expression correlates with the mesenchymal glioma stem cells marker CD44 and predicts poor survival in GBM when both genes are upregulated." (PMID 32340135, 2020).
glioblastoma (5 papers, 2014 to 2026). The most malignant astrocytic tumor (WHO grade IV). "Knocking out MKNK1 can alleviate phosphorylated eIF4E and tumour formation in glioblastoma U87MG cells." (PMID 37864471, 2023).
Glucose intolerance (2 papers, 2016 to 2021). Glucose intolerance (GI) can be defined as dysglycemia that comprises both prediabetes and diabetes. "MAP kinase-interacting kinases MNK1(Mknk1) is a target gene of miR-370-3p, which reported that the HFD-fed MNK1-knockout (KO) mice protected against diet-induced glucose intolerance and insulin resistance compared to HFD-fed wild-type animals." (PMID 34834018, 2021).
Insulin resistance (2 papers, 2016 to 2021). Increased resistance towards insulin, that is, diminished effectiveness of insulin in reducing blood glucose levels. "Previous studies have shown that knockdown of Mknk1 in mice can improve insulin resistance in mice with obesity metabolic syndrome and can promote glucose metabolism in mice." (PMID 34834018, 2021).
multiple myeloma (2 papers, 2014 to 2015). "It was shown in multiple myeloma (MM) cells that the activity of the c-Myc IRES was dependent on the MAP kinase MNK1 (MAPK-interacting serine/threonine kinase 1) and the IRES-trans-acting factor HnRNPA1 (an RNA binding protein)." (PMID 26539410, 2015).
Wilms tumor (2 papers, 2021 to 2023). An embryonal neoplasm characterized by the presence of epithelial, mesenchymal, and blastema components. "However, in Wilm’s tumor mouse model, an anti-tumor effect of miRNA-483-5p, a mimic of which markedly induced tumor cell apoptosis via downregulation of MKNK1 and upregulation of cleaved caspase 3 and cleaved PARP levels, was shown." (PMID 37108073, 2023).
diabetes (1 paper, 2023). "In support of our findings, previous studies of transcriptome analyses of diabetes-prone and diabetes-resistant obese mice disclosed that the downregulation of MKNK1 in pancreatic islets is associated with diabetes." (PMID 36982812, 2023). "The upregulation of MKNK1, Frataxin (FRDA), and electron transfer flavoprotein-ubiquinone oxidoreductase (ETFD) can help decrease the risk of diabetes mellitus." (PMID 36982812, 2023).
Iron deficiency (1 paper, 2019). "Iron deficiency altered methylation at the genes regulating ephrin B signaling/ephrin receptor signaling (data not shown), including increased methylation at Ephb1, Itsn1, Prkar1b, and Srgap2, and decreased methylation at Arhgef15, Mknk1, and Slit3 loci." (PMID 31137889, 2019).
metabolic syndrome (1 paper, 2021). A cluster of metabolic risk factors for CARDIOVASCULAR DISEASES and TYPE 2 DIABETES MELLITUS. "In addition, MAP kinase-interacting serine/threonine kinase 1 (Mknk1) has shown that knockout Mknk1 in mice could prevent against the metabolic syndrome." (PMID 34834018, 2021).
preeclampsia (1 paper, 2023). Preeclampsia is a hypertensive disorder of pregnancy that is characterized by new-onset hypertension with proteinuria presenting after 20 weeks of gestation, and depending on mild or severe forms may initially present with severe headache, visual disturbances, and hyperreflexia. "In summary, our study identified MKNK1, ARNT, FLT1, SERPINE1, ENO3, LDHA, BCL2 out of HIF1-signaling pathway as novel diagnostic biomarkers for preeclampsia patients, and a diagnostic signature based on these genes is constructed for preeclampsia." (PMID 37020283, 2023). "Seven genes (including MKNK1, ARNT, FLT1, SERPINE1, ENO3, LDHA, BCL2) were screen out to build potential diagnostic model of preeclampsia." (PMID 37020283, 2023). "MKNK1 was found significantly increased in FGR-affected placenta, while its function in preeclampsia remained to be investigated." (PMID 37020283, 2023).
cancer (44 papers, 2014 to 2025). A tumor composed of atypical neoplastic, often pleomorphic cells that invade other tissues. "Problem 1 asked teams to predict molecules that bound the RETM955T-associated cancer targets RET[M918T], BRAF, SRC, S6K, and avoided binding to MKNK1, TTK, ERK8, PDK1, and PAK3." (PMID 34520464, 2021). "The KIRP N-model includes an isoform in the MAP kinase MKNK1, suggesting a similar involvement in cancer as MKNK2." (PMID 27535130, 2016). "Previous studies have revealed that MKNK1 can phosphorylate eukaryotic initiation factor 4E (eIF4E) and co‐regulate various cellular processes, and essentially regulate the progression of different cancers." (PMID 37864471, 2023). "However, research on the sncRNA modulation of MKNK1 is limited, and only a few studies reveal that miRNAs can target MKNK1 to affect cancer progression." (PMID 37864471, 2023). "Among the interesting downregulated proteins found in treated MCF-7 is MAP kinase-interacting serine/threonine-protein kinase 1 (MKNK1), this protein may have a role in the response to cytokines and environmental stress, which may provide an effective strategy for cancer therapy." (PMID 29085821, 2017). "MKNK1 is a serine/threonine kinase and a member of the MAPK subfamily, essential for cancer development and progression, and has potential clinical applications." (PMID 37864471, 2023). "In this present study, two SNPs (MKNK1 rs8602, GREM1 rs10318) were previously reported in the context of cancer prognosis." (PMID 33658398, 2021). "Problem 1 asked participants to predict molecules that bound the RETM955T-associated cancer pro-targets RET[M918T], BRAF, SRC, S6K, and did not bind the anti-targets MKNK1, TTK, ERK8, PDK1, and PAK3." (PMID 34520464, 2021). "EIF4E is phosphorylated by MKNK1/2, which are downstream of the RAS/RAF/MEK/ERK and p38 signaling pathways, and is a major cap-binding protein involved in the regulation of mRNA translation in normal and cancer development." (PMID 29188469, 2018).
tumor (43 papers, 2012 to 2025). "Whether tumor recurrence is related to mutations in MKNK1, POLE, RET, RTEL1, RUNX1T1, TAP1 still requires further research for validation." (PMID 40901169, 2025). "Therefore, the MAPK signalling pathway and MKNK1 are closely linked with the incidence and development of tumours." (PMID 37864471, 2023). "Specifically, ERK1/2 and p38MAPK can directly phosphorylate and activate MKNK1, promoting MKNK1‐mediated eIF4E phosphorylation, protein synthesis, tumour cell proliferation and metastasis." (PMID 37864471, 2023). "This investigation indicated that tRF‐16‐7X9PN5D could affect CRC cells' radiation resistance by targeting MKNK1, which has important guiding significance for tumour radiotherapy." (PMID 37864471, 2023). "In addition to the pro-survival and anti-apoptotic functions in tumor cells, YB-1 has been shown to play critical roles in drug resistance by transactivating drug resistance-associated genes including MDR1, MRP2 and MKNK1." (PMID 25993060, 2015). "However, among the class III gene mutation testing results, the genes with higher abundance mutations include MKNK1, POLE, RET, RTEL1, RUNX1T1, TAP1, indicating that these gene mutations may be related to sex-cord-stromal tumors or require further research to explore unknown tumor subtypes." (PMID 40901169, 2025). "Merestinib is a potent inhibitor of NTRK, it also targets additional kinases such as the TAM receptors (AXL, MERTK, and TYRO3), and MKNK1 and MKNK2, which may also contribute to anti-tumor growth." (PMID 30885237, 2019). "It is important to point out that while merestinib is a potent inhibitor of NTRK, it also targets additional kinases such as the TAM receptors (AXL, MERTK, and TYRO3), and MKNK1 and MKNK2, which may also contribute to anti-tumor growth." (PMID 29568395, 2018).
MKNK1 also shares sentences with these, for which no sentence is quoted: melanoma (13 papers); infection (9); prostate carcinoma (8); lung carcinoma (6); nasopharyngeal carcinoma (5); colorectal cancer (4); lymphoma (4); Anxiety (3); breast tumor (3); hepatocellular carcinoma (3); lung adenocarcinoma (3); non-small cell lung carcinoma (3); triple-negative breast carcinoma (3); acute myeloid leukemia (2); astrocytoma (2); autism (2); autism spectrum disorder (2); chronic myeloid leukemia (2); depression (2); diffuse large B-cell lymphoma (2); lung squamous cell carcinoma (2); lymph node metastasis (2); ovarian carcinoma (2); adenocarcinoma (1); angiomyolipoma (1); Arthritis (1); autoimmune (1); bladder cancer (1); bladder tumors (1); cardiac hypertrophy (1).
A further 28 diseases each share a sentence with MKNK1 in 1 paper.